TOE1 (target of EGR1, exonuclease)
Description:
Inhibits cell growth rate and cell cycle. Induces CDKN1A expression as well as TGF-beta expression. Mediates the inhibitory growth effect of EGR1. Involved in the maturation of snRNAs and snRNA 3'-tail processing.
Synonyms: hCaf1z; TOE-1; PCH7
Tractability: PROTAC: ubiquitination databases record sites on it; its protein half-life has been measured.
Gene: Protein-coding gene on chromosome 1 (45,340,012 to 45,343,976, forward strand). Ensembl gene ENSG00000132773.
Subcellular location: Nucleus, nucleolus; Nucleus speckle
Subcellular location (Human Protein Atlas): Nucleoplasm; Nuclear bodies
Gene Ontology:
Molecular function: 3'-5'-RNA exonuclease activity; poly(A)-specific ribonuclease activity; protein binding; snRNA binding; metal ion binding; nucleic acid binding
Biological process: snRNA 3'-end processing; RNA metabolic process
Cellular component: Cajal body; cytoplasm; nuclear speck; nucleolus
Genetic constraint (gnomAD): Loss-of-function variants: 50 observed, 51.67 expected, observed/expected ratio (o/e) 0.97, 90% interval 0.77 to 1.23. The upper end of that interval is the gene's LOEUF score, 1.23, which puts it in group 5 of 6, group 1 being the genes least tolerant of losing a copy. Missense variants: 544 observed, 689.39 expected, observed/expected ratio (o/e) 0.79, 90% interval 0.74 to 0.85. Synonymous variants: 221 observed, 262.35 expected, observed/expected ratio (o/e) 0.84, 90% interval 0.75 to 0.94.
Homologues: Orthologues: chimpanzee TOE1 (99% identical), macaque TOE1 (94% identical), dog TOE1 (87% identical), guinea pig TOE1 (87% identical), pig TOE1 (86% identical), rabbit TOE1 (86% identical), rat Toe1 (83% identical), mouse Toe1 (82% identical), tropical clawed frog toe1 (51% identical), zebrafish toe1 (50% identical), Caenorhabditis elegans parn-2 (30% identical). Paralogues in human: PARN (17% identical), PNLDC1 (17% identical).
Diseases named in the same sentence as TOE1 in open-access papers:
TOE1 is named in the same sentence as 21 diseases in open-access papers, as found by Europe PMC text mining. Sharing a sentence is not in itself a finding about the gene and the disease. The quoted sentences say what the papers report.
pontocerebellar hypoplasia (4 papers, 2020 to 2024). Pontocerebellar hypoplasias (PCH) are a rare heterogeneous group of diseases characterized by hypoplasia and atrophy and/or early neurodegeneration of the cerebellum and pons. "Pontocerebellar Hypoplasia 7–associated protein TOE1 is a key 3′ end maturation factor for canonical Pol II snRNAs, but how it distinguishes substrate from non-substrate RNAs has remained unknown." (PMID 38194449, 2024). "The importance of the DEDD family deadenylases is underscored by genetic mutations in PARN and TOE1 genes leading to specific subtypes of human disorders dyskeratosis congenita and pontocerebellar hypoplasia (PCH), respectively." (PMID 32499401, 2020).
pontocerebellar hypoplasia type 7 (3 papers, 2023 to 2026). "Over a dozen missense mutations in the TOE1 gene have been linked to Pontocerebellar Hypoplasia Type 7 (PCH7), a rare but serious neurodevelopmental and neurodegenerative disease that leads to early mortality." (PMID 42178111, 2026). "Finally, biallelic loss-of-function mutations in TOE1 (TOE1 mutants) cause Pontocerebellar Hypoplasia type 7 (PCH7), a unique recessive syndrome characterized by neurodegeneration with ambiguous genitalia." (PMID 37544646, 2023). "Functions of these enzymes are central to human health, with TOE1 mutations associated with Pontocerebellar Hypoplasia Type 7 (PCH7), PARN mutations with Dyskeratosis Congenita and other human disorders, PNLDC1 mutations with azoospermia, and USB1 mutations with Poikiloderma with neutropenia." (PMID 38194449, 2024).
development (1 paper, 2021). "At least two neurological disorders with PCH have already been observed in combination with a disorder of sexual development: PCH7 due to bi-allelic variants in TOE1 (OMIM # 614969, *613931) and Joubert syndrome 1 due to bi-allelic variants in INPP5E (OMIM # 213300, *613037)." (PMID 33168985, 2021).
dyslipidemia (1 paper, 2024).
hypogonadism (1 paper, 2019). A disorder characterized by decreased function of the gonads. "Of the 10 known PCH subtypes, PCH7 (MIM: 614969) appears associated with hypogonadism and was recently linked to mutations in the gene encoding TOE1 (target of Egr1, also known as hCaf1z)." (PMID 30371886, 2019).
myeloid leukemia (1 paper, 2026). A clonal proliferation of myeloid cells and their precursors in the bone marrow, peripheral blood, and spleen. "AML samples exhibited deregulated TOE1 expression versus normal hematopoietic stem/progenitor cells (HSPCs), and TOE1 depletion suppressed the proliferation of myeloid leukemia cell lines, and primary human HSPCs, partly through a p21-activated-kinase 2 (PAK2) mediated mechanism." (PMID 42030941, 2026).
tauopathy (1 paper, 2023). Neurodegenerative disorders involving deposition of abnormal tau protein isoforms (tau proteins) in neurons and glial cells in the brain. "In C. elegans, loss of parn-2, an ortholog of TOE1, partially suppressed tauopathy." (PMID 37544646, 2023). "Together, these data suggest that there is a link between tauopathy, TOE1, and poly(A) RNA metabolism." (PMID 37544646, 2023).
TOE1 also shares sentences with these, for which no sentence is quoted: dyskeratosis congenita (2 papers); neurological disease (2); developmental delay (1); Fanconi anemia (1); Hypertonia (1); Hypotonia (1); Joubert syndrome 1 (1); microcephaly (1); neurodegenerative disease (1); neutropenia (1); poikiloderma with neutropenia (1); Primary microcephaly (1); tumor (1); urofacial syndrome (1).